TRIM24 (tripartite motif containing 24)
Diseases named in the same sentence as TRIM24 in open-access papers (continued):
Sharing a sentence is not in itself a finding about the gene and the disease.
tumor (continued). "The loss of Trim24 in myeloid cells dramatically promoted tumor growth." (PMID 31554795, 2019). "Recently, growing evidence implicated the involvement of TRIM24 in tumor progression." (PMID 29862279, 2018). "Numerous studies have indicated TRIM24 contributes to the regulation of tumor cell biology through interactions with tumor suppressor or oncogenic pathways." (PMID 41430038, 2025). "Taken together, these results indicated that the tumor became less reliant on the TRIM24::NTRK2 oncogenic driver over time and had the capacity to activate other oncogenic signaling pathways." (PMID 41331048, 2025). "In order to examine TRIM24’s function in GC cells in vivo, an orthotopic tumor mouse model of GC was established using vector-luciferase or knockdown TRIM24-luciferase lentivirus-transfected MKN74 and NUGC3 GC cells." (PMID 41430038, 2025). "We identified a rare TRIM24::NTRK2 fusion in the primary tumor, which enabled a targeted TRK-inhibitor treatment." (PMID 41331048, 2025). "Taken together, our scRNA‐sequencing results showed that TRIM24 overexpression markedly affected both intratumoral heterogeneity and the tumor microenvironment." (PMID 38828688, 2024). "NU7441 treatment also decreased the protein expression of the tumor cell proliferation markers Ki‐67 and the TRIM24 downstream effector ATF3." (PMID 38828688, 2024). "Medium expression of GFAP and limited expression of S100 and OLIG2 were detected in the NHA/HRasV12/TRIM24 S767/768A‐derived tumor xenografts." (PMID 38828688, 2024). "Subsequent NGS of tumor RNA identified a TRIM24::MET fusion between exon 12 of TRIM24 and exon 15 of MET on chromosome 7 involving the MET tyrosine kinase domain." (PMID 38902810, 2024). "In this study, we show that animals bearing HRasV12/TRIM24‐driven GBM tumor xenografts treated with the DNA‐PKcs inhibitor NU7441 achieved prolonged survival – almost twice that of the control group." (PMID 38828688, 2024). "Using single‐cell RNA‐sequencing (scRNA‐Seq), the authors show that TRIM24 overexpression impacts both intratumoral heterogeneity and the tumor microenvironment." (PMID 38828688, 2024). "Instead, depletion of TRIM24 in macrophages promoted tumor growth, and also reversed the inhibitory effect of USP7 overexpression." (PMID 38129408, 2023). "A cell line (TR.1) established from a Trim24-Ret positive tumor exhibited high in vitro sensitivity to the RET inhibitors LOXO-292 and BLU-667 and orthotopic TR.1 cell-derived tumors underwent marked shrinkage upon LOXO-292 treatment." (PMID 37470475, 2023). "More importantly, a previous study has demonstrated the upregulation of TRIM24 in CRC tumor samples, and it is associated with several clinical parameters, such as tumor size, stage, and poor prognosis." (PMID 36551703, 2022). "Due to the heterogeneity of tissue differentiation, TRIM24 acts as a tumor suppressor or tumor promoter in different tumors." (PMID 35105347, 2022). "Consistently, Western blot analysis showed that TRIM24 was elevated by 1.62-fold in CRC tumor samples (n = 10), compared with their normal counterparts." (PMID 36551703, 2022). "Next to the nuclear TRIM24 expression, the cytoplasmatic TRIM24 expression has also been described in some tumor entities." (PMID 35743773, 2022). "In a first step, we analyzed the differences of the cytoplasmatic TRIM24 expression in the different tumor tissues." (PMID 35743773, 2022).
tumor (continued). "And dTRIM24 has successfully degraded TRIM24 in human metaplastic breast cancer patient-derived xenografts to decrease tumor cell viability." (PMID 36100865, 2022). "We further demonstrate that TRIM24 potentiates the tumour promoting function of STAT1 in HNSCC cells." (PMID 35595823, 2022). "The results showed that the tumor volume of TRIM24 overexpression group was significantly larger than that of control group." (PMID 35105347, 2022). "Further, the tumour inhibitory effects mediated by TRIM24 inhibition were significantly greater than STAT1 inhibition." (PMID 35595823, 2022). "The average tumor volume of the TRIM24 overexpression group was nearly three times than that of the control group, namely 233.1 mm3 versus 86.5 mm3 (P < 0.05)." (PMID 35105347, 2022). "Another study found that TRIM16, TRIM32, TRIM24, TRIM8, TRIM27, TRIM11, and PML are associated with cancer stem cells and the clinical prognosis of RCC, and affect tumor progression." (PMID 36261847, 2022). "TRIM24 is a member of the transcription intermediary factor family and plays important roles in T cell differentiation, innate immune regulation, and tumor development." (PMID 35653796, 2022). "So, an improved follow-up schedule should be employed not only for 18 months but for a longer time after the primary treatment if the tumor is TRIM24+." (PMID 35743773, 2022). "Global and single-cell tumor profiling reveal Met as a direct oncogenic target of TRIM24, leading to aberrant PI3K/mTOR activation." (PMID 34508101, 2021). "As an explanation for higher TRIM24 expression in tumor cells, epigenetic silencing of miR-137 via methylation of promoter proximal CpG islands was suggested." (PMID 34208621, 2021). "In fact, both TRIMs’ aberrant overexpression in BC is correlated with poor survival of BC patients, and depletion of these TRIMs leads to reduced cell proliferation, as has been shown for tumor-derived BC cells for TRIM24 and MCF7 cells for TRIM56." (PMID 34208621, 2021). "Trim24 level was markedly higher in patients with a tumor diameter <5 than in those with a tumor diameter ≥5 and also higher in patients with I-II TNM stage than in those with III–IV TNM stage." (PMID 33336072, 2020). "Trim24 binds to chromatin and estrogen receptors, which in turn activates estrogen-dependent genes involved in tumor cell proliferation and tumor progression." (PMID 33336072, 2020). "Another tripartite motif protein, TRIM24, was initially described as a liver-specific tumor suppressor." (PMID 32660118, 2020). "To validate this finding, we evaluated the expression of TRIM24 in tumor and paired peri‐tumoral tissues at the protein level." (PMID 32677374, 2020). "Similar to TRIM24, an increased expression of TRIM59 has been demonstrated in CRC samples and is associated with advanced tumor stage of CRC patients." (PMID 33066016, 2020). "It was found that silencing of NCK1-AS1 or up-regulation of miR-138-2-3p led to increased TRIM24 expression and decreased tumor formation speed in mice, while the further over-expression of TRIM24 promoted the tumor formation speed (all p < 0.05)." (PMID 32293515, 2020). "Statistical results indicated that the high expression rate of Trim24 in tumor tissue reached 60.4% (29/48), which was markedly higher than that in paraneoplastic tissues, 27.1% (13/48)." (PMID 33336072, 2020). "We performed ChIP‐PCR assays in tumor tissues to detect interactions between TRIM24 and the YAP promoter in vivo." (PMID 32677374, 2020).
tumor (continued). "Similar to TRIM23, the overexpression of TRIM24 which is synonymously known as transcription intermediary factor 1α (TIF1α), positively correlates with tumor size and shorter survival time of CRC patients as indicated by Kaplan–Meier survival analysis." (PMID 33066016, 2020). "Our data contributed to expanding the knowledge of Trim24 functions in promoting tumor progression, suggesting that Trim24 was a potential target for the treatment therapy of human RCC." (PMID 33336072, 2020). "Due to the critical tumor-promoting function of M2-like TAMs, we propose that targeting Trim24 or downstream Stat6 acetylation has clinical potential in cancer immunotherapy." (PMID 31554795, 2019). "By contrast, Stat6 mediates the suppression of TRIM24 expression in M2 macrophages to contribute to the induction of an immunosuppressive tumor niche." (PMID 31554795, 2019). "Our results show that increased TRIM24 in HNSCC plays an important role in tumor metabolism and progression, possibly through regulation of GLUT3 and cyclin D1." (PMID 29862279, 2018). "Further, KI-67 staining was reduced in TRIM28-knockdown tumors and was partially rescued in TRIM24-reexpressing tumors, being concordant with their respective tumor growth rates." (PMID 30479348, 2018). "Next, to examine TRIM28 protein levels in primary patient tissues and to evaluate its correlation with TRIM24, we performed immunohistochemistry (IHC) in human PCa tumor progression tissue microarrays (TMA)." (PMID 30479348, 2018). "TRIM24 can act as either a tumor suppressor or oncogene depending on the type of cancer and recognizes acetylated H3 lysine 23 (H3K23ac)." (PMID 30591655, 2018). "We found that TRIM28-knockdown cells showed retarded xenograft tumor growth and ectopic re-expression of TRIM24 in these cells partially rescued xenograft tumor growth." (PMID 30479348, 2018). "Like many other TRIM proteins, TRIM24 has been reported to exhibit both tumour suppressor and oncogenic properties in a cell type dependent context." (PMID 29110249, 2018). "Collectively, our data present the new evidence to show that miR-511 serves as a tumor suppressor in GC through negatively regulating TRIM24 expression." (PMID 28114950, 2017). "Mounting evidence showed TRIM24 has a key role in the modulation of the biological and clinical behavior of tumor cells through interaction with tumor-suppressive or oncogenic pathways." (PMID 28114950, 2017). "Because our signaling analysis was generated using GLUT4-silenced HNSCC cells, we proposed that GLUT4 triggers TRIM24 to repress several downstream tumor suppressors." (PMID 28061796, 2017). "In our previous study, we found TRIM24 was upregulated in GC and its overexpression promoted tumor malignant behaviors via activation of Wnt/β-catenin pathway." (PMID 28114950, 2017). "In this study, our findings indicate that TRIM24 functions as a tumor suppressor in ESCC, which is conflicting with some reports on other cancers." (PMID 27689360, 2016). "Survival analysis also display that 5-year OS and 5-year DFS of patients with high TRIM24 level are 64.4% and 57.2%, compared with 35.8% and 28.9% of those with low level, respectively, which hint that TRIM24 is a tumor suppressor in ESCC patients." (PMID 27689360, 2016). "Recent studies reveal that TRIM24 is upregulated in glioblastoma and gastric cancer, and promotes tumor growth and induces chemotherapy resistance via the phosphatidylinositide 3-kinase (PI3K)/Akt pathway." (PMID 27689360, 2016). "When patients were stratified by tumor size (5 cm as a cutoff), we found that TRIM24 expression is a prognostic factor for OS (P = 0.003) and DFS (P = 0.002) in patients with tumor less than 5 cm, but not in those with tumor larger or equal to 5 cm." (PMID 27689360, 2016). "TRIM24 expression was detected in nuclear compartments of tumor cells, while normal tissues or benign liver lesion tissues exhibited negative or low staining." (PMID 24409330, 2014).
tumor (continued). "While other TRIM proteins, such as TRIM27/RFP and TRIM24/TIF1α, function normally as tumour suppressor proteins, but acquire oncogenic activity when fused to kinases by tumour-associated chromosomal rearrangements." (PMID 23404198, 2013). "High expression of TRIM24 in the locally advanced HNSCC indicates it is common event in the tumor type." (PMID 23717505, 2013). "TRIM24 expression was observed in nuclear compartments of tumor cell, while the normal bronchial epithelia and pneumocytes exhibited negative or low staining." (PMID 22666376, 2012). "Whereas none to weak staining for TRIM24 was detected in the normal lung tissues, a strong staining of TRIM24 was detected in adjacent tumor cells." (PMID 22666376, 2012). "CRISPR knockout of the TRIM24::NTRK2 fusion gene also showed tumor reliance on the VEGFR pathway." (PMID 41331048, 2025). "Given that TRIM24 is recognized as a ubiquitin E3 ligase that promotes the ubiquitination of numerous substrates, including some tumor suppressors, thereby exerting its oncogenic effects, our study focused on the proteins whose expression increased after TRIM24 knockdown." (PMID 41430038, 2025). "TRIM24 silencing induced tumor regression in NRF2-active LUSC tumors and patient-derived organoids." (PMID 40676628, 2025). "While many studies have reported that miRNAs can directly target TRIM24 and regulate its roles in cell proliferation, tumor formation, and inflammation, this is the first identification of the macrophage polarization regulation pathways miR‐137‐3p/TRIM24/STAT6." (PMID 41395781, 2025). "Importantly, elevated TRIM24 levels correlated with advanced tumor stage and poorer clinical outcomes." (PMID 41430038, 2025). "In the second case, RNA-based NGS performed on the recurrent tumor revealed a TRIM24::MET fusion between exon 12 of TRIM24 (NM_015905.2) and exon 15 of MET (NM_000245.3) and a gain of chromosome 7 without any evidence of further genetic alterations, especially no signs of CDKN2A/B deletion." (PMID 38902810, 2024). "In this study, we report a novel role for TRIM24 in Ep‐GBM‐like tumor formation." (PMID 38828688, 2024). "Ectopic expression of TRIM24 in immortalized human mammary epithelial cells (HMECs) significantly enhances cellular proliferation and induces malignant transformation, as evidenced by xenograft tumor growth." (PMID 39160596, 2024). "Furthermore, in an orthotopic intracranial NHA/HRasV12/TRIM24 tumor xenograft model, we treated tumor‐bearing immunodeficient mice with NU7441 via intraperitoneal injection." (PMID 38828688, 2024). "Based on these, we propose the hypothesis that M35L mutation possibly exchanges SPOP substrates from oncoproteins (such as GLI2, c-MYC and TRIM24) to tumor suppressors (such as IRF2BP2), therefore reprogramming the tumor properties of SPOP." (PMID 38409107, 2024). "Interestingly, elevated TRIM24 levels in HCC samples correlate with higher tumor grade and reduced AMPK expression." (PMID 39160596, 2024). "In recent years, studies have found that TRIM28 could regulate tumor progression and promote tumor growth by enhancing TRIM24 stability." (PMID 36690975, 2023). "Notably, in the B16 melanoma tumour model, STAT6 has been demonstrated to induce M2 macrophage polarization and mediate the suppression of TRIM24 expression in M2 macrophages, contributing to the induction of an immunosuppressive tumour niche." (PMID 37491279, 2023). "Our results indicate that cytoplasmatic TRIM24 may play an important role in the tumor biology of HNSCCs." (PMID 35743773, 2022). "Interestingly, TCGA data showed that TRIM24 was upregulated by 1.75-fold in CRC tumor samples, and there was a positive correlation between TRIM24 and DDX27 in CRC tumor samples." (PMID 36551703, 2022). "Interestingly, despite the increase in STAT1 induced by TRIM24 knockdown, we observed that TRIM24 silencing inhibited the tumour promoting effects and enhanced the tumour inhibitory effects of STAT1 activation." (PMID 35595823, 2022).
tumor (continued). "It is possible that TRIM24 inhibition could directly or indirectly inhibit the tumorigenicity of HNSCC tumour cells." (PMID 35595823, 2022). "We found TRIM24 to be expressed not only in the nuclei of tumor cells but also in the cytoplasm." (PMID 35743773, 2022). "However, a caution from recent studies is that TRIM24 can function as either a tumour suppressor or an oncogene in a cancer-type dependent manner." (PMID 35803934, 2022). "In addition, tumorigenic experiments in nude mice confirmed the discovery of proliferation experiments in vitro, and showed that TRIM24 knockdown inhibited tumor growth in vivo." (PMID 35105347, 2022). "We found TRIM24 to be expressed in the nuclei of HNSCC tumor cells as well as in the cytoplasm." (PMID 35743773, 2022). "Thus, TRIM24 presents itself as a potential target for modulating STAT1 expression in the tumour microenvironment." (PMID 35595823, 2022). "Similarly, the results of Wurmbach, Mas,21 and Guichard23 all implied that TRIM24 increased significantly in HCC tumor tissues compared with normal samples, which is consistent with the results of TCGA liver statistics." (PMID 35142083, 2022). "For example, miR-655 may suppress the proliferation of PCa cells and tumor metastasis by inhibiting TRIM24 and miR-30a may inhibit the androgen-independent growth of PCa cells by targeting the expression levels of MYBL2, FOXD1, and SOX4." (PMID 35782093, 2022). "Moreover, colony formation and CCK-8 assays showed that TRIM24 promoted EOC cell growth, and tumorigenic experiments in nude mice showed that TRIM24 knockdown inhibited tumor growth in vivo." (PMID 35105347, 2022). "Furthermore, the relative expression of TRIM24 was higher and miR-655 was lower in the resected tumor tissues of Lv-Linc00963-WT group than Lv-control group (P<0.05)." (PMID 33643926, 2021). "Here, we find that pharmacological inhibition of these pathways in primary Trim24COE tumor cells and TRIM24-PROTAC treatment of MpBC TNBC PDX tumorspheres decreased cellular viability, suggesting potential in therapeutically targeting TRIM24 and its regulated pathways in TRIM24-expressing TNBC." (PMID 34508101, 2021). "In addition, Trim24 was significantly upregulated in RCC, and its high expression was negatively associated with the tumor size." (PMID 33336072, 2020). "However, in the analysis of the relationship between clinicopathological information and Trim24 expression, the expression of Trim24 in tumor tissues with a smaller diameter was significantly higher than that with a larger diameter." (PMID 33336072, 2020). "Taken together, these data showed that IL-4-activated Stat6 directly suppresses TRIM24 gene expression during macrophage M2 polarization, which may in turn contribute to immunosuppressive profiles in the context of the tumor microenvironment." (PMID 31554795, 2019). "In this study, we showed that GLUT4 overexpression promotes tumor metastasis and is significantly associated with poor prognosis in HNSCC patients through a glucose-indirect pathway in cancer cells that leads to the activation of the TRIM24 pathway." (PMID 28061796, 2017). "Moreover, the association of TRIM24 with H3K23ac is important for EGFR-stimulated cell proliferation, cell migration, colony formation, tumor growth, GSC self-renewal, p-STAT3, ID1 expression and the binding of TRIM24, H3K23ac and STAT3 with ID1 promoter." (PMID 29129908, 2017). "TRIM24 has been shown to function as an oncogene or tumor suppressor dependent on the context." (PMID 29129908, 2017). "All of the evidence demonstrates that TRIM24 functions as a tumor suppressor in ESCC." (PMID 27689360, 2016). "However, in transgenic mice models, TRIM24 is demonstrated as a tumor suppressor and can suppress liver carcinogenesis via interacting with RARα." (PMID 27689360, 2016).